KANK1 (KN motif and ankyrin repeat domains 1)
Diseases named in the same sentence as KANK1 in open-access papers (continued):
Sharing a sentence is not in itself a finding about the gene and the disease.
cancer (15 papers, 2017 to 2025). A tumor composed of atypical neoplastic, often pleomorphic cells that invade other tissues. "It has been documented that KANK1 inhibited cancer development by blocking the Rho-associated protein kinase (ROCK) pathway and the β-catenin pathway." (PMID 34349117, 2021). "This study has robustly demonstrated that high KANK1 expression is associated with good prognostic characteristics and improved BC patients’ outcomes, which is in agreement with other cancers including gastric, nerve and lung." (PMID 31679074, 2020). "To further explore the mutation nature and scope of KANK1 locus deletions, we analyzed human cancer genomic data using cBioportal26." (PMID 28067315, 2017). "SOX5, KANK1, and ZFHX3 are transcription factors implicated in specific cancer entities and regulate cell development, migration, and genomic stability." (PMID 40456839, 2025). "Although KANK1 was shown to suppress cancer cell growth in vitro, TCGA database points to high KANK1 levels associated with poor prognosis in a wide spectrum of human malignancies." (PMID 39613731, 2024). "This is in concordance with previous reports indicating that reduced expression of KANK1 facilitates metastasis in different types of cancer and further reinforces its role as a prognostic indicator." (PMID 31679074, 2020). "In the comprehensive prognostic signature, genes such as NFKB2, DLK1, KANK1, play important roles in cancer biology." (PMID 33193606, 2020). "Consistent with our MTT assay, we found that KANK1 upregulation led to a reduction of colony formation numbers, suggesting that KANK1 is able to reduce independent growth capacity, a key characteristic of human cancers." (PMID 28067315, 2017). "The role of the focal adhesion protein KANK1 in cancer progression is not yet clearly understood." (PMID 39613731, 2024). "Our findings indicate that KANK1 localization at the cell-cell junction of LECs from multilayered carcinomas leads to NOS1AP binding, disassembly of the SCRIB/NOS1AP complex, which profoundly compromises SCRIB’s ability to activate the Hippo pathway and stabilizes TAZ." (PMID 39613731, 2024). "KANK1 plays an important role in the development of many malignant tumours." (PMID 31679074, 2020). "This allow KANK1 to integrate alongside with β-catenin aiming to regulate its distribution in the nucleus and concentrate its transcription, therefore, affecting the development of cancer." (PMID 31679074, 2020). "As cancer cells usually survive in a stressful environment in vivo, we reasoned that restoring KANK1 in such stressful condition might give more insight to its function." (PMID 28067315, 2017). "Additionally, another study showed that in certain cancers such as ALL KANK1 is completely deleted." (PMID 37731134, 2023). "Thus, we KANK1[circle674459-674907] may also have a role in cancer prognostic assessment." (PMID 39850493, 2024). "It was revealed that several top up‐regulated genes such as KANK1, GALNT14, TMEM98, and PTPN3 and top down‐regulated genes such as PITX2, SNCA, and EPHA7 play key roles in cancer progression and chemotherapy response." (PMID 37937323, 2023). "Several immune-related genes exhibited marked variation: for example, CD84 and SMAD3 were abundant in T7 but almost undetectable in T15, whereas KANK1, often relevant in cancer prognosis, was highly expressed in T6 and T15 but absent in T7." (PMID 40764306, 2025). "Several immune-related genes showed pronounced variation: for example, CD84 and SMAD3 were abundant in T7 but nearly undetectable in T15, whereas KANK1, often relevant in cancer prognosis, was highly expressed in T6 and T15 but absent in T7." (PMID 40162205, 2025). "Similarly, seven genes (SGCZ, KANK1, KDM4C, KCNMA1, ZNF263, CDH4, NCAM2) contain partial CNV duplications in both BD‐cancer and BD‐only patients, but the deleted loci are different." (PMID 39140252, 2025).
cancer (continued). "Consequently, we recommend a spotlight on chromosome 9 aberrations affecting DOCK8 and KANK1 in NB, and especially on the sometimes denigrated FSCAs, as they could involve invasion in MNA HR-NB, as occurs in other malignant tumors." (PMID 33109237, 2020).
neurodevelopmental disorder (6 papers, 2017 to 2025). A behavioral and cognitive disorder with onset during the developmental period that involves impaired or aberrant development of intellectual, motor, or social functions. "A meta-analysis of copy-number variant association studies found a significant duplication in KANK1 in those with five different neurodevelopmental disorders, including MDD41." (PMID 39994233, 2025). "A recent study sought to identify copy number variants across five neurodevelopmental disorders, and detected an enrichment for chromosome 9p24.3 duplication encompassing DOCK8 and KANK1 in affected individuals." (PMID 29241461, 2017). "Further analysis on CNV shows enrichment of de novo CNVs for both PLXNB1 and KANK1 gene within ASD and neurodevelopmental disorder cases." (PMID 34802461, 2021).
infection (2 papers, 2019 to 2023). The state of being infected such as from the introduction of a foreign agent such as serum, vaccine, antigenic substance or organism. "To examine this hypothesis, we need to perform more detailed functional analysis to assess the activity of Kank1−/− immune cells in response to infections in in vitro and in vivo experimental settings, which would be interesting to address in future studies." (PMID 37895296, 2023).
kidney disease (2 papers, 2024). "As it is predicted that those with KANK1 gene mutations are more likely to develop kidney diseases, it is important for people with KANK1 gene mutations to be aware of the risk of developing kidney diseases and to strive to protect their kidneys." (PMID 38891998, 2024).
central nervous system disorder (1 paper, 2021). A disease involving the central nervous system. "The mutated KANK1 may develop the central nervous system disorder (cerebral palsy spastic quadriplegic type 2)." (PMID 34446027, 2021).
KANK1 also shares sentences with these, for which no sentence is quoted: lung carcinoma (2 papers); malignant peripheral nerve sheath tumor (2); psychiatric diseases (2); albuminuria (1); astrocytoma (1); benign schwannoma (1); Brain atrophy (1); clear cell renal cell carcinoma (1); developmental delay (1); epilepsy (1); Glomerular sclerosis (1); head and neck tumors (1); hematological malignancy (1); hyperthyroidism (1); keloid (1); Kernicterus Spectrum Disorders (1); language disorder (1); Latent infections (1); low grade glioma (1); lung adenocarcinoma (1); nasopharyngeal carcinoma (1); Pitt-Hopkins syndrome (1); pleomorphic xanthoastrocytoma (1); renal angiomyolipoma (1); Sepsis (1); small cell lung carcinoma (1); stomach cancers (1); trigonocephaly (1).